TGFB2 (transforming growth factor beta 2)
Diseases named in the same sentence as TGFB2 in open-access papers (continued):
Sharing a sentence is not in itself a finding about the gene and the disease.
gastric cancer (continued). "In this study, we analyzed the transcriptomic dataset GSE184336 of 231 gastric cancer patients, and the results showed that TGFβ1, TGFβ2 and TGFβ3 were highly expressed in cancer tissues, and western blot assays further confirmed the differences in TGFβ expression." (PMID 36119489, 2022). "In this study, we comprehensively analyzed TGFβ1, TGFβ2 and TGFβ3 and gastric cancer microenvironmental features, including immune cell infiltration, EMT, hypoxia, mutation, immunotherapy and drug treatment, based on HMUCH sequencing data (GSE184336) and public databases." (PMID 36119489, 2022). "In the gastric cancer microenvironment TGFβ2 is closely related to tumor stemness, EMT and stroma." (PMID 35620459, 2022). "Finally, we established risk model based on key pathways ligands TGFB2, VEGFB, COL10A1, AREG and EFNA5 to predict gastric cancer survival." (PMID 34332586, 2021). "TGFβ2 is also a valuable prognostic biomarker in gastric cancer patients." (PMID 34790823, 2021). "This suggests that TGFβ2 is a key factor which governs immune cell recruitment to gastric cancer tumours, potentially playing a vital role in governing immune cell infiltration and thus representing a valuable prognostic biomarker in gastric cancer patients." (PMID 32530106, 2020). "In summary, TGFβ2 may be an important regulator of immune cell infiltration and a valuable prognostic biomarker in gastric cancer patients." (PMID 32530106, 2020). "Besides, the interplay of miR-141 and oncogenic TGFβ2 was found to orchestrate malignancy in gastric cancer." (PMID 33100909, 2020). "We determined TGFβ2 expression to be significantly correlated with outcome in multiple types of cancer in the Cancer Genome Atlas (TCGA), with the effect being particularly pronounced in gastric cancer." (PMID 32530106, 2020). "However, there are fewer studies on TGFβ2 and its methylation in gastric cancer." (PMID 35620459, 2022). "However, there are few studies on TGFβ2 and its methylation in gastric cancer." (PMID 35620459, 2022). "The high responsiveness of ICB when TGFβ2 is highly expressed suggests that the detection of TGFβ2 expression can predict the response of gastric cancer patients to immune checkpoint inhibitors and may serve as a candidate target for gastric cancer immunotherapy." (PMID 35620459, 2022). "In gastric cancer dataset STAD, GSE63089 and dataset GSE184336, the expression levels of TGFβ1, TGFβ2 and TGFβ3 were higher in cancer tissues than in normal tissues adjacent to the cancer." (PMID 36119489, 2022). "The results of this study showed that TGFβ1, TGFβ2 and TGFβ3 were positively correlated with EMT, CDH2, VIM and ZEB1 and significantly negatively correlated with CDH1 in multiple gastric cancer datasets." (PMID 36119489, 2022). "The expression levels of TGFB1, TGFB2, ZEB1 and PTBP1 were detected by qRT-PCR in 92 pairs of gastric carcinoma specimens and adjacent normal tissues (Cohort 2)." (PMID 34706749, 2021). "Thus, after silencing the TGFβ gene in gastric cancer cells, the progression of EMT was significantly inhibited, and all of these results together suggest that TGFβ1, TGFβ2 and TGFβ3 are key factors in regulating the progression of EMT." (PMID 36119489, 2022). "Survival analysis showed that high expression of TGFβ2 and hypomethylation levels of TGFβ2 were negative factors in the prognosis of gastric cancer." (PMID 35620459, 2022).
Marfan syndrome (20 papers, 2014 to 2025). A disorder of the connective tissue. "Aortic dilatation in patients with Marfan syndrome is associated with key molecular changes, including decreased levels of TGFβ2 and its receptors, TGFβR1 and TGFβR2." (PMID 40243722, 2025). "TGFB2 variants result in a phenotype overlapping with Marfan syndrome and are associated with thoracic aneurysms and mitral valve prolapse, while TGFB3 variants present with craniofacial anomalies, joint laxity, and aortic dilation." (PMID 40981152, 2025). "In the aortic tissue of patients with familial ATAA, Marfan syndrome, or patients who have mutations in TGFB2, TGFB3, TGFBR or SMAD3, increased TGFB signaling was reported." (PMID 37238945, 2023). "mitral valve prolapse (MVP) with mitral regurgitation has been observed in individuals with TGFB2 mutations (such as Loeys–Dietz Syndrome), although less frequently than in the Marfan syndrome." (PMID 33801433, 2021). "TGFB2 encodes the protein Transforming Growth Factor β2 (TGF β2) which is observed to be upregulated in Marfan syndrome, Loeys-Dietz syndrome, and cutis laxa, which are associated with aneurysmal changes with histological features including smooth muscle cell apoptosis." (PMID 36584111, 2022). "Mutations in MYLK cause a vascular disease that is different both from that in Marfan syndrome and from that associated with mutations that disrupt TGF-β signaling pathways (mutations in TGFβR1, TGFβR2, SMAD3, TGFβ2, TGFβ3)." (PMID 27586135, 2016). "Therefore, our objective was to assess the mRNA expression of FBN1, TGFBR1, TGFBR2, and TGFB2 in the aortic tissue of Marfan syndrome patients with aortic dilation." (PMID 40243722, 2025). "Historically, the understanding of heritable TAAD was anchored in syndromic disorders such as Marfan syndrome (caused by pathogenic FBN1 variants) and LDS (linked to TGFBR1, TGFBR2, SMAD3, SMAD2, TGFB2, and TGFB3), conditions defined by clear Mendelian inheritance patterns and systemic features." (PMID 40981152, 2025). "Loeys–Dietz type 4: LDS type 4/TGFB2 is the most similar to Marfan syndrome." (PMID 34680857, 2021). "Reduction of TGFβ2 by various means alleviates Marfan syndrome." (PMID 25917920, 2015). "Causative genes include autosomal polycystic kidney disease (PKD1, PKD2), Ehlers–Danlos syndrome (COL3A1), Marfan syndrome (FBN1), Loeys–Dietz syndrome (TGFB2, TGFB3, TGFBR1, TGFBR2, SMAD2, SMAD3), and Majewski Osteodysplastic Primordial Dwarfism (PCNT)." (PMID 40004483, 2025). "A more comprehensive understanding of the disease would require detailed genetic characterization beyond FBN1, including TGFB2, its receptors (TGFBR1, TGFBR2), and other genes involved in Marfan syndrome and related disorders." (PMID 40243722, 2025). "Marfan syndrome (MFS) is associated with FBN1 mutations; Ehlers–Danlos syndrome (EDS) is relevant to the COL3A1 mutation; Loeysؘ–Dietz syndrome (LDS) is related to TGFBR1 or TGFBR2 mutations as well as SMAD3 or TGFB2 mutations." (PMID 36291545, 2022). "Among them, 51 patients had genetically confirmed HTAD (Marfan syndrome (FBN1), Loeys-Dietz syndrome (TGFBR1, TGFBR2, SMAD3, TGFB2), vascular Ehlers-Danlos syndrome (COLSA1), and non-syndromic HTAD (ACTA2, MYH11, MYLK))." (PMID 41310758, 2025).
asthma (19 papers, 2007 to 2025). "TGFB2 has also been found to be expressed mainly in eosinophils, and greater expression of TGFB2 has been identified to be associated with persistent eosinophilic inflammation (severe asthma) in human." (PMID 34256695, 2021). "Expression of isoforms of TGFβ 1 - 3 cytokines is influenced by tagging single nucleotide polymorphisms (SNPs) in the TGFβ1, TGFβ2 and TGFβ3 genes, which may be associated with asthma and other diseases." (PMID 35774789, 2022). "Expression of isoforms 1–3 of TGFβ cytokine is influenced by tagging polymorphisms in the TGFβ1, TGFβ2 and TGFβ3 gene, and these SNPs may be associated with the risk of asthma development and severity as well as with other diseases." (PMID 34620181, 2021). "In this study, one of the asthma-associated promoter variants, −109 →ACAA ins, was a common variant (allele frequency 0.292) and was shown to increase TGFB2 promoter reporter activity in the BEAS2B bronchial epithelial cell line." (PMID 22970254, 2012). "Since the TGFβ2 isoform acts on the same receptors and signal via the same AR-Smads as TGFβ1, these results indicate that TGFβ2 is also a likely candidate to explain activation of Smad signaling in asthma." (PMID 17892594, 2007). "Our purpose was to determine whether genotypes of MAC/SNP TGFβ1, TGFβ2, and TGFβ3 are related to the level of asthma control, measured with the application of the Asthma Control Test (ACTTM) in asthmatics and healthy controls." (PMID 34620181, 2021). "Their functions and effects on the expression of TGFβ1, TGFβ2 and TGFβ3 mRNA, as well as a new pool not yet studied in asthma, had been known before." (PMID 35774789, 2022).
fibrosis (18 papers, 2011 to 2026). the formation of excess fibrous connective tissue in an organ or tissue in a reparative or reactive process. "Expression of Tgfβ2, and Ctgf genes involved in cardiac fibrosis was upregulated in TmcsMed1-/- mouse heart." (PMID 27548259, 2016). "Interestingly, in our study, both BMP3 and TGFB2 expressions were increased in the severe fibrosis group and correlated positively with the degree of fibrosis in LSGs from SS patients." (PMID 34400910, 2021). "We found that levels of TGFB2/TGFB2‐OT1 were highly increased in serum samples of patients with a NAS ≥ 5 and fibrosis F = 3‐4." (PMID 31169972, 2019). "We validated the up‐regulation of UBE2V1, BNIP3L mRNAs, RP11‐128N14.5 lncRNA, TGFB2/TGFB2‐OT1 coding/lncRNA in patients with NAS ≥ 5 (vs NAS ≤ 4) and the up‐regulation of HBA2 mRNA, TGFB2/TGFB2‐OT1 coding/lncRNA in patients with Fibrosis stages = 3‐4 (vs F = 0‐2)." (PMID 31169972, 2019). "Another four studies revealed that the serum TGFB2/TGFB2-OT1, lnc-SPARCL1-1:2, lncRNA RABGAP1L-DT-206, MALAT1, Neat1, and HULC expression were significantly higher in patients with advanced fibrosis/cirrhosis (F = 3–4) than in those without it (F = 0–2)." (PMID 36979495, 2023).
Loeys-Dietz syndrome (18 papers, 2014 to 2025). Loeys-Dietz syndrome is a rare genetic connective tissue disorder characterized by a broad spectrum of craniofacial, vascular and skeletal manifestations with four genetic subtypes described forming a clinical continuum. "In this study, we explore several variants that occur near splice junctions of TGFB2, a gene linked to the connective tissue disorder Loeys-Dietz Syndrome." (PMID 39737004, 2024). "Heterozygous mutations in TGFB2 are associated with syndromic and nonsyndromic forms of aortic aneurysm, including Loeys-Dietz syndrome (LDS) and nonsyndromic aortic disease (NSAD)." (PMID 33418956, 2021). "One patient (ScPT0443400X) with a TGFB2 variant, which is mutated in Loeys-Dietz syndrome (LDS), has hypermobility, Chiari malformation (mother and sister also affected) and reports easily bruising." (PMID 33125268, 2020). "Several of the symptoms, also seen in Loeys-Dietz Syndrome, are consistent with TGFB2 mutations." (PMID 39480826, 2024). "Similarly, mutations in Tgfβ2 and Tgfβr1 cause microretrognathia in Loeys-Dietz syndrome, mutations in Tgfβr2 and Smad2 cause jaw length defects, and TGFβ signaling has been shown to be essential for patterning the proximal portion of the murine dentary." (PMID 35666955, 2022). "Among the genes queried, COL3A1 and aggregated testing of Loeys-Dietz syndrome-associated genes (TGFBR1, TGFBR2, SMAD2, SMAD3, TGFB2, TGFB3) were the leading signals of enrichment, consistent with prior studies [21•, 24, 25]." (PMID 37979122, 2023). "These include syndromic diseases associated with aortic aneurysms, including Marfan’s and Loeys Dietz Syndromes (LDS), due to mutations in TGFβ signaling genes FBN1, TGFBR1, TGFBR2, TGFB2, and TGFB3." (PMID 30307970, 2018). "Among these, Loeys-Dietz syndrome (MIM # 609,192) shows mutations in other genes which are involved in the same pathway of FBN1 and include TGFBR1 (MIM * 190,181), TGFBR2 (MIM * 190,182), SMAD3 (MIM * 603,109), TGFB2 (MIM * 190,220), TGFB3 (MIM * 190,230) and SMAD2 (MIM * 601,366)." (PMID 39008115, 2024). "Finally, we did not consider genes encoding TGF-beta ligands TGFB2 and TGFB3, or SMAD2, although these were described recently to contribute to Loeys-Dietz syndrome." (PMID 31795342, 2019).
osteosarcoma (18 papers, 2007 to 2025). A usually aggressive malignant bone-forming mesenchymal neoplasm, predominantly affecting adolescents and young adults. "Moreover, exosomes from metastasis osteosarcoma cells have been shown to alter tumor-associated macrophage cellular signaling, boost the M2 phenotype, and establish an immunosuppressive, tumor-promoting milieu via producing TGFB2." (PMID 35978902, 2022). "Osteosarcoma-exosomes facilitate M2 polarization in the tumor microenvironment by upregulating TGFβ2 signaling." (PMID 40443670, 2025). "And LYN, TNC, TGFB2, IGFBP1were up-regulated in the osteosarcoma tissue samples, while IGFBP4, TAGLN, SERPINE1, ANPEP were down-regulated." (PMID 35665757, 2022). "Circ_0000285 acts as a ceRNA that increases TGFB2 expression by sponging hsa-miRNA-599 in osteosarcoma." (PMID 33154193, 2020). "Moreover, miR-153 reduces the expression of TGFβ2 and acts as a tumor suppressor in osteosarcoma, albeit the administration of a therapy targeting this miRNA has not been investigated thus far." (PMID 33498521, 2021). "Lumican inhibited osteosarcoma cell adhesion through endogenous inhibition of TGFβ2." (PMID 28332606, 2017). "Meanwhile, the levels of TGFB2, p-Smad2, p-Smad3, and BMP-6 showed a reverse trend after the SRI-011381 application, suggesting that PNO1 could influence the progression of osteosarcoma cells via the TGF-β signaling pathway." (PMID 38071381, 2023). "However, the relative expression levels of LYN, TNC, TGFB2, and IGFBP1 were significantly higher in the osteosarcoma group compared with the normal group (P < 0.05)." (PMID 35665757, 2022).
atherosclerosis (17 papers, 2015 to 2025). A disease characterized by the build-up of fatty material and calcium deposition in the arterial wall resulting in partial or complete occlusion of the arterial lumen. "Unsupervised DEGs analysis of SMCs revealed increased expression in Abcb8ECKO of TGF-β-pathway genes such as Tgfb1, Tgfb2, Tgfb3, Mmp2 and Col1a1, inflammatory genes such as Ccl2 (encoding for MCP1) and Csf1 as well as atherosclerosis-associated genes including Egr1, Sqstm1, Irf1, Sox4 and Xylt1." (PMID 41252867, 2025). "In rat atherosclerosis PCR array, Abca1, Bax, Bcl2, Bcl2a1, Cd44, Fabp3, Hbegf, Lypla1, Ptgs1, Selplg, Tgfb2, Tnc, and Vegfa had reverse trend between WT and MU groups, while the trends of Bcl2l1, Bid, Birc3, Cxcl1, Fas, Fn1, Itga2, Itga5, Lif, Nfkb1, Nr1h3, Ppard, and Sod1 were consistent." (PMID 34545275, 2021). "PCR-Array: mRNA expression of 16 of 84 atherosclerosis-related genes were significantly regulated at least 2-fold by IL-1α alone in comparison to control (p<.05), ranging from 8.3-fold (SELPLG) to 108.4-fold (TGFB2) up-regulation." (PMID 28323859, 2017).
keloid (17 papers, 2004 to 2024). An irregularly shaped, elevated mark on the skin caused by deposits of excessive amounts of collagen during wound healing. "By contrast, a down-regulation of TGFB2 (0.47-fold) was observed, factor which higher activity was related to keloids." (PMID 29867527, 2018). "In a separate study, the addition of exogenous TGFb2 resulted in strong upregulation of Col1 and Col3 in keloid and burn hypertrophic scars." (PMID 22235299, 2012). "CD8 T cells, macrophages, NK cells, B cells, and TGFB2 expression were significantly different in two subtypes of keloids (P-value<0.05), demonstrating that they could be studied in depth as important targets for treatment." (PMID 37168863, 2023). "Fibroblasts in keloids may specifically interact with macrophages and other MPs via TGFB2–TGFBR2, TGFB3– TGFBR3, CCL2-CCR1, and CCL2-CCR5 binding, which play inhibitory roles on the target cells." (PMID 35990663, 2022).
colon cancer (14 papers, 2014 to 2024). "We found that multiple cancer types exhibited a significant association between patient prognosis and TGFβ2 expression including breast, lung, blood, ovarian, prostate, brain and colon cancer." (PMID 32530106, 2020). "TGFB2 is frequently mutated in colon cancer and associated with carcinogenesis." (PMID 35991839, 2022). "Altogether the hypermethylated CEACAM5 group showed these clinical features resemble the CMS1 classification of CRC with a BRAF mutation, TGFB2 mutation, MSI‐H, and proximally located colon tumor." (PMID 37942534, 2024). "Moreover, our data indicated that the hypermethylated CEACAM5 group showed molecular pathological features with a BRAF mutation, TGFB2 mutation, MSI‐H, and proximally located colon tumors that were similar to CMS1 tumors." (PMID 37942534, 2024). "In colon cancer, BMP7 is common overregulated gene, as are TGFB2, TGFBI, and TGIF2, which might be involved in the regulation of SOX4." (PMID 39228892, 2024). "Surprisingly, in view of the very different cell types, we found that US7 cells with ST6Gal1 overexpression had 19 genes in common (18 increased and one decreased) with the SW948 ST6Gal1 overexpressing colon cancer cells, including, among others, ST6GAL1, TGFβ2, and CTF1." (PMID 35371997, 2022).
renal fibrosis (14 papers, 2011 to 2025). A final common manifestation of a wide variety of chronic kidney diseases characterized by glomerulosclerosis and tubulointerstitial fibrosis. "Given prior reports linking Tgfbr2 deletion to enhanced MF recruitment, the Rtn3-null induced loss of the Tgfb2-Tgfbr1/2 axis suggests potential hyper-activation of MFs, resulting in renal fibrosis." (PMID 38937317, 2024). "The independent role of TGFβ2 and TGFβ3 in XLAS associated renal fibrosis is therefore worthy of further investigation." (PMID 40075271, 2025). "TGFβ1 and TGFβ2 are the major isoforms involved in renal fibrosis." (PMID 28002484, 2016). "Our study observed a concurrent upregulation of all three isoforms and interestingly a relatively higher upregulation of TGFβ2 than TGFβ1/TGFβ3 in both tissues and cells, possibly suggesting that TGFβ2 may critically contribute to XLAS associated renal fibrosis." (PMID 40075271, 2025).